CP (ceruloplasmin)
Diseases named in the same sentence as CP in open-access papers (continued):
Sharing a sentence is not in itself a finding about the gene and the disease.
tumor (continued). "The study found that both CP-liposomes and GMCP-liposomes effectively decreased tumor size, demonstrating their potential for enhanced CBD delivery in cancer treatment." (PMID 41304881, 2025). "The data showed that CP-SkP2 and CP-SkP5 significantly increased the OS of the KPC mice, and reduced tumor size in the pancreata." (PMID 40588478, 2025). "Specifically, the hot tumour (C4) has the highest MHC score, while the cold tumour (C2) displayed the highest suppressor cell (SC) and immunomodulator (CP) enrichment scores." (PMID 41292185, 2025). "Our study revealed that LINC02936 promotes tumor progression and suppresses ferroptosis in EC by binding to SIX1 and upregulating CP expression." (PMID 38385087, 2024). "ATF3-transgenic mice with orthotopic breast cancer, which showed enhanced tumor growth, exhibited increased cardiac expression of periostin, CTGF, FN, SerpinA3, and CP." (PMID 38279150, 2024). "In this study, we introduce a hybrid nanozyme, termed Fe‐MOF/CP, composed of iron metal‐organic framework (Fe‐MOF) nanoparticles, biological ChOx, and PEGylation, for integrated ferroptosis‐immune tumor therapy." (PMID 39120559, 2024). "Fe‐MOF/CP retains the POD and GSHox‐mimicking activities of Fe‐MOF, which induce cellular ferroptosis by generating tumor‐specific ROS and depleting GSH." (PMID 39120559, 2024). "In our study, we introduce Fe‐MOF/CP, a hybrid nanozyme based on Fe‐MOF, engineered for tumor ferroptosis and immunotherapy by strategically incorporating ChOx into Fe‐MOF nanoparticles." (PMID 39120559, 2024). "Given that CP expression is closely related to ferroptosis 15, 16, and that CP is a ferroptosis suppressor gene based on the FerrDb database 20, we speculated that the elevated expression of CP might be related to the suppression of ferroptosis and promotion of tumor progression in EC cells." (PMID 38385087, 2024). "Tumor Immune Estimation Resource (TIMER) and CIBERSORT analyses indicated a substantial correlation between the CP expression and infiltration of immunocytes in the TME." (PMID 37637428, 2023). "Co-localization of CP and CA9 proteins using IF staining validated tumor cell-specific CP expression." (PMID 36973268, 2023). "Like CP-DN-ATF5, owing to its penetratin-like sequence, ST101 is rapidly taken up by cultured tumor cells and when delivered peripherally into mice, can pass the blood–brain barrier and undergo cellular uptake." (PMID 36831248, 2023). "After cellular uptake, CP-DDA NPs precisely released DAS and Pt(II) due to the hydrolysis of ester bonds and redox degradation of GSH in the tumor, thereby displaying potent synergistic antitumor activity and reduced toxicities of free drugs." (PMID 37894544, 2023). "The resulting cell-penetrating dn peptide for ATF5, CP-dn-ATF5, inhibits survival/growth of a wide variety of cultured tumor cell types and blocks or slows tumor growth and prolongs survival in multiple mouse cancer models." (PMID 34065488, 2021). "Some new tumor-specific markers for different pathologic types of RCC, such as SPOCK1, PTGIS, REG1A, CP and SPAG4 were identified and validated." (PMID 34722263, 2021). "As a result of the greater tumor burden, the unfavorable response cohort exhibited worse liver function markers (e.g., ALBI grade, AAPR, CP, albumin, and alkaline phosphatase) and BCLC stage at baseline than the favorable response group." (PMID 34336728, 2021). "Restoration of miR-145-5p by miRNA mimics transfection decreases CP expression, increases Fe2+ and PHD1/2 levels and HIF hydroxylation while reduced HIF-2α levels resulting in the inhibition of tumor angiogenesis." (PMID 32708433, 2020). "Finally, to control for the possibility that CP-dn-ATF5 kills survivin over-expressing tumor cells by a mechanism apart from its dn-ATF5 activity, we also asked whether survivin over-expression would rescue cells transfected with the pLe-GFP-FLAG-dn-ATF5 plasmid." (PMID 31551409, 2019).
tumor (continued). "The mean intra-tumor doxorubicin concentration in the SP90-LD group was 12.0-, 2.2- and 2.6-fold higher than that in the FD, LD and CP-LD groups, respectively." (PMID 23776619, 2013). "PDLIM3 was significantly upregulated in the stroma of CP‐s, but no change was observed between CP‐i and CP‐s in the tumour, and CA1 and APM2 remained in a similar mode of abundance changes in the tumour and stroma between CP‐i and CP‐s groups." (PMID 40697100, 2025). "For PDLIM3, the results of IHC in the stroma are comparable to those of MS, and its abundant responses to CP in IHC in the tumour are different from its signals gained from MS PDLIM3 increases in CP‐s in IHC but no change in MS." (PMID 40697100, 2025). "Notably, a significant difference is observed between C1 of CP‐s and CP‐i groups, implying that the DEP‐based parameters are sensitive to protein changes in the tumour region." (PMID 40697100, 2025). "TAC evaluated tumor morphology, biology, and liver function by combining TBS, AFP, and CP." (PMID 38611104, 2024). "Mechanistically, LINC02936 enhances CP expression by binding to the transcription factor SIX1, which reduces intracellular Fe2+ and ROS levels and suppresses ferroptosis in EC, thus promoting tumor progression." (PMID 38385087, 2024). "Moreover, while CP-DN-ATF5, BPEP, DPEP and ST101 all show significant anti-tumor activity in in vivo models, for the most part, they appear to slow the growth of tumors rather than eradicate them." (PMID 36831248, 2023). "Consistent with this, our data demonstrate the number of atoms showing a significant correlation between HelperTs and Tumor cells is lowered in PDAC as opposed to CP (p-val = 0.0329)." (PMID 36541756, 2022). "Compared with other treatment groups, the CP@NP-cRGD and AZD9291 group exhibited the slowest tumor growth curves and showed the strongest antitumor effect, suggesting that CP@NP-cRGD could effectively surmount drug resistance to AZD9291 in vivo." (PMID 36015232, 2022). "We further found that CP had been used as a target for four tumor drugs, while ZEB1 did not have targeted drugs yet." (PMID 35232428, 2022). "While the body weight of the free CP group fell, the weights were nearly unchanged in the PEG-MMP-PLG-Pt cohort, demonstrating the reduction in off-target side effects in addition to increased anti-tumor apoptotic activity and survival time." (PMID 36077371, 2022). "This may be because CP-bi-apt can specifically bind to PD-L1 highly expressed tumor cells and CD16-positive NK cells, which may further assist to direct NK cells into the tumor site." (PMID 35228895, 2022). "The group of mice that received CP combination therapy (with and without gold nanoparticles) showed a significant reduction in the size of tumor when compared to the Pacli alone treatment and control groups." (PMID 35216264, 2022). "It showed subgroup comparison regarding tumor size but not CP class or number of tumor lesions had significant differences for 1- and 2-year OS rates and 1-, 2-, and 3-year LC rates." (PMID 33832536, 2021). "Thus, the results identified some new tumor-specific markers and verified SPOCK1, PTGIS, REG1A, CP and SPAG4 in different types of RCC." (PMID 34722263, 2021). "Tumour cells 2 had highly expressed CA9 and CP but lowly expressed NDUFA4L2." (PMID 34168986, 2021). "On the other hand, our experiments indicated that death of tumor cells promoted by CP-dn-ATF5 was not rescued by survivin over-expression." (PMID 31551409, 2019). "Preliminary studies of IgG, IgA, IgM, ceruloplasmin and C-reactive protein suggested that these would not be valuable monitors of tumour burden." (PMID 6158966, 1980). "Among the proteomic markers, elevated levels of serum ceruloplasmin, MYO1B, salivary CPLANE1, serum albumin, HSP 27, gamma actin, SCC 1, and A4, serum SNCG and SCCAg and immune cell markers such as, IL‐6, TNF‐α, and CD4 + T cell were suitable proteomic tumor markers in detecting OSCC." (PMID 40256126, 2025).
tumor (continued). "CP is a reported tumor marker for ccRCC36–38 but PCSK6 is not." (PMID 36973268, 2023). "Finally, we discovered that the 12 IMRGs expression had significant differences, among which SFXN3, TFR2, TMPRSS6, HMOX1, and LCN2 expressions were elevated in the cancer group, and SCARA5, LTF, STEAP2, SLC39A14, CP, ALAS2, and TF were low expressed in the tumor group." (PMID 37361050, 2023). "Previous research found that immunophenoscore (IPS) can be used to evaluate tumor immunogenicity and predict the response to immune checkpoint inhibitor, which was classified into four categories, including MHC molecules (MHC), immunomodulators (CP), effector cells (EC) and suppressor cells (SC)." (PMID 36339001, 2022). "On the other hand, olaparib showed strongly additive effects in reducing tumor growth when used in combination with cisplatin, while not being very effective as a single agent (olaparib alone 1865.63 ± 93.25 mm3, p = 0.07 vs. CP+Olaparib 641.28 ± 32.05 mm3, p = 0.002)." (PMID 35321693, 2022). "Superior antitumor activity of co-loaded PTX/CP drug micelles compared to single drug micelles, or their mixture, was demonstrated in cisplatin-resistant human ovarian carcinoma A2780/CisR xenograft tumor and multidrug-resistant breast cancer LCC-6-MDR orthotopic tumor models." (PMID 35237155, 2022). "The inability of survivin over-expression to rescue tumor cells from the lethal effects of dn-ATF5 exposure raised the question of whether CP-dn-ATF5 might kill tumor cells by a non-apoptotic mechanism." (PMID 31551409, 2019). "Tumour cells with upregulated proteins involved in cell proliferation are thought to be targeted by CP, whereas those with a higher abundance of proteins involved in energy metabolism may not be specifically bound by CP." (PMID 40697100, 2025). "In addition, CP nanodots also presented favorable enhanced EPR effect, significant tumor accumulation, and pH-dependent ·OH generation, which could effectively suppress tumor growth with minimal side effects in vivo." (PMID 36903549, 2023). "A Tukey's post hoc test determined that the percent large (>10 mm2) neoplasm was higher in mice fed a Western diet without supplements (23.5 ± 9.8%) compared to the percent large neoplasms in mice fed a control diet with a propolis supplement (8.2 ± 6.5%, P = 0.043) (W vs. CP)." (PMID 27265242, 2016). "A Tukey's post hoc test revealed that the percent small (< 5 mm2) neoplasms was lower in mice fed a Western diet without supplements (42.3 ± 10.6%) compared to the percent small neoplasms in mice fed a control with a propolis supplement (64.8 ± 8.2%, P = 0.030) (W vs. CP)." (PMID 27265242, 2016). "Further examination of the IHC signals in the tumour and stroma between CP‐i and CP‐s revealed that TFRC and PDLIM3 displayed significantly increased abundance in CP‐s, but not in CP‐i, and ALDH5A1 and APM showed no significant changes between CP‐i and CP‐s." (PMID 40697100, 2025). "For example, CP and ITGA10 were upregulated exclusively in GFP+ versus DsRed+ tumor cells but not at all by in vitro exposure to hypoxia." (PMID 31649238, 2019).
cancer (125 papers, 1992 to 2025). A tumor composed of atypical neoplastic, often pleomorphic cells that invade other tissues. "The association between copper ion and cancer has been established over many years, with studies consistently showing elevated levels of copper ion and ceruloplasmin in cancers or the serum of animal models and cancer patients." (PMID 39430913, 2024). "Increased levels of serum ceruloplasmin, copper’s main carrier protein, are associated with angiogenesis and have been found in various cancers." (PMID 36978391, 2023). "Ceruloplasmin is associated with the invasiveness and prognosis of these cancer types through different molecular mechanisms and signaling pathways." (PMID 34413268, 2021). "KEGG enrichment analysis further suggested that the Wnt/β-catenin signaling pathway was implicated in the anti-cancer and anti-metastasis mechanisms of CP during progression of HBV-associated HCC." (PMID 34168559, 2021). "We also performed GO enrichment and KEGG analysis using DAVID database to further investigate the anti-cancer mechanisms of CP in HBV-associated HCC." (PMID 34168559, 2021). "Ceruloplasmin is an adipokine with an increased expression in the adipose tissue of obese patients, as well as in cells present in obesity-associated cancers." (PMID 33287452, 2020). "They noted that the overall incidence of cancer was positively associated with serum ceruloplasmin levels." (PMID 33287452, 2020). "Notably, NCOA4 exhibited relevance with pathways concerning allograft rejection and NOD-like receptor signaling, while CP was associated with complement and coagulation cascades, focal adhesion, and pathways in cancer." (PMID 38887322, 2024). "Of note, besides that of CP, expression of other metalloenzymes including TF, MT-1 and MT-2 is also increased in BM in the present study, all described to up-regulated by HIFs and associated to carcinogenesis and cancer treatment resistance." (PMID 38006431, 2023). "CP has been linked to carcinogenesis and cancer progression; however, the underlying molecular mechanisms of CP remain unknown." (PMID 32708433, 2020). "Results gleaned from overexpression studies of human CP mutations in HCT116 cancer cells and expressing corresponding human CTC1 mutations into CTC1−/− MEFs strongly suggest that CP is due to failure to properly maintain the telomeric C‐strand, leading to telomere replication defects." (PMID 29774655, 2018). "The overall incidence of cancer was positively associated with serum ceruloplasmin level." (PMID 1739632, 1992). "Indeed, the incidence of cancer development is associated with serum ceruloplasmin levels in several types of cancers, implying that serum ceruloplasmin levels may be a predictive hallmark for cancer development." (PMID 38398797, 2024). "Moreover, 3′- UTR has been revealed to be effective RNA-based therapy tools for treating cardiac diseases irrespective of its cognate protein, the findings in this study suggested that mutated SLC7A11, GPX4 and CP 3′-UTRs may be effective RNA-based therapeutic targets for DOXIC in cancer patients." (PMID 40915108, 2025). "In light of the observed pH disequilibrium between the intracellular and extracellular pH in various cancers, we investigated the pH regulation pathways in CP-CIDs and NCP-CIDs." (PMID 40724918, 2025). "Increased C4B and C8A levels were correlated with cancer-associated inflammation and CRC progression, while cancer-associated inflammation was linked to the acute-phase reactant leucine-rich alpha-2-glycoprotein 1 (LRG1) and ceruloplasmin." (PMID 38911905, 2024). "MDROs were most often found in between the time of cancer diagnosis and up to 100 days after cancer diagnosis, except for CP-GNB, which were found in a bimodal pattern with peaks directly after cancer diagnosis and 2 years after cancer diagnosis." (PMID 37980302, 2024). "Ceruloplasmin plays key roles not only in the transport of Cu, but also in the formation of novel blood vessels in cancer tissues." (PMID 38398797, 2024).
cancer (continued). "After 0, 24, 48, and 72 h, mitochondrial activity, cancer cell membrane CP levels, cell growth, and caspase-3 activity were assessed in aliquots of Jurkat and MTC-SK cells." (PMID 38891069, 2024). "In obese cancer patients, there can be changes in analytes such as adiponectin, adipokines, leptin, ceruloplasmin, etc.." (PMID 37378223, 2023). "CP is a multifunctional molecule involved in iron metabolism and plays a role in cancer as it is involved in angiogenesis and neovascularization." (PMID 37284310, 2023). "An in-silico analysis was performed to predict the anticancer potential of moricin in cancer cells using Anti CP and ACP servers based on a support vector machine (SVM)." (PMID 37344820, 2023). "Impedance-based real-time cell analysis (RTCA) showed that the recorded cell index (CI), which correlated with the reported cell proliferation potential of the cancer cells, significantly decreased in the CP-FaP2 and CP-FaP3 treated PANC-1 cells." (PMID 36797256, 2023). "Intriguingly, several studies reported that cuproptosis-related genes, such as ATOX1 and CP, can affect the progression of cancer." (PMID 36211378, 2022). "Both in vitro and in vivo experiments demonstrate that CP‐NPs can not only kill cancer cells efficiently upon light irradiation, but also avoid phototoxicity after PDT treatment via self‐degradation induced ROS generation “switch‐off”." (PMID 34898054, 2022). "The bioinformatics analysis showed that CP was involved in cell growth and death, which was closely related to cancer." (PMID 36276156, 2022). "We found weaker functional connectivity between the right DLPFC and the right ACC in the CP+ group compared to the CP− group, and this functional connectivity showed a positive correlation with the duration of cancer pain." (PMID 36072897, 2022). "We further analyzed ceruloplasmin expression based on individual cancer stages and found that ceruloplasmin expression was closely correlated with stage 2 BRCA." (PMID 34413268, 2021). "To assess the anti-cancer effects of CP on HCC cells, we first employed CCK-8 assay on several representative HCC cell lines (HepG2, SMMC-7721 and Huh-7) and a normal hepatic cell line (HL-7702)." (PMID 34168559, 2021). "Taken together, our study not only provided a supporting evidence for the anti-metastasis activities of CP against HBV-associated HCC, but it also addressed the novel role of Cav-1 in mediating the Akt/GSK3β/β-catenin axis during advanced cancer stages." (PMID 34168559, 2021). "First, the mRNA levels of ceruloplasmin in common cancers and adjacent/normal tissues were investigated according to the TIMER online database." (PMID 34413268, 2021). "We focused on three proteins: two down-regulated proteins (ceruloplasmin and C6) and one up-regulated protein (haptoglobin) because these proteins show significant p-value difference between cancer and healthy controls." (PMID 32620920, 2020). "Here, we report on several additional unanticipated biological properties of polybia‐CP and derivatives, namely their ability to target Plasmodium sporozoites and cancer cells." (PMID 33005737, 2020). "Previously it was reported that 20S proteasomes harboring a mixed assortment of cP and iP catalytic subunits exist in cancer cells and that their PI sensitivity differs from those of standard cP or iP5." (PMID 30858500, 2019). "Although in our study malignant tumors and tumors of grade 2 and 3 based on CP and HP showed higher values of cytomorphometric parameters, these results were not statistically significant." (PMID 29360854, 2018). "Patients who were pregnant and those with malignant tumors, and infectious and inflammatory diseases had significantly higher mean serum CP levels." (PMID 29324775, 2018).